CD40 (CD40 molecule)
Diseases named in the same sentence as CD40 in open-access papers (continued):
Sharing a sentence is not in itself a finding about the gene and the disease.
tumor (continued). "Therefore, we next examined whether IL-2/anti-CD40 was effective in young vs. elderly AE17 tumor-bearing mice and whether macrophages contributed to the efficacy of IL-2/anti-CD40 immunotherapy." (PMID 30459812, 2018). "Furthermore, young, but not elderly, IL-2/CD40-treated mice demonstrated additional reductions in other regulatory markers expressed by tumor-associated CD4+ T cells, including ICOS and IL-10." (PMID 30560130, 2018). "IL-2/CD40 slowed tumor growth in both age groups (completely in young, partially in elderly) and this may be explained by our observations that IL-2/CD40 induced several common effects on tumor-infiltrating CD11c+ cells, CD8+ T cells, and CD4+ T cells from both age groups." (PMID 30560130, 2018). "Our results indicated that anti-CD40 could stimulate B lymphocytes from tumor bearing mice, which led to an increase in the expression of proteins in the antigen presentation machinery and activation of secondary responses in T lymphocytes previously exposed to tumor antigens." (PMID 29975708, 2018). "This post-chemotherapy activity of agonistic anti-CD40 is hypothesised to occur by activating DC that have become ‘loaded’ with antigen from chemotherapy-induced tumour cell death, inducing expression of costimulatory molecules CD80 and CD86 and increased production of IL12 amongst other cytokines." (PMID 28619093, 2017). "Therefore, through immune system activation, targeting of CD40 can affect tumour growth." (PMID 28640192, 2017). "However, it remains to be clarified which DC subsets may be involved in anti-CD40 mediated tumour immunity." (PMID 28619093, 2017). "In addition, immune checkpoint inhibitors like CTLA-4, the PD-1/PD-L1 axis, and CD40 could overcome the suppressive microenvironment of the tumour, and prevent T cell exhaustion and apoptosis." (PMID 27427766, 2016). "In addition to DCs, CD40 antibodies also activate other myeloid cells and the activity can also depend on complement-mediated cytotoxicity (CMC) or antibody-dependent cell-mediated cytotoxicity (ADCC), or even be immune effector independent when CD40 is expressed on tumor cells." (PMID 27656185, 2016). "Our data herein demonstrate that combining CD40-activating immunotherapy with sunitinib treatment enhances DC activation, decreases the number of MDSCs and induces endothelial activation, leading to increased infiltration of cytotoxic T-cells into tumor tissue and reduced tumor growth." (PMID 27385210, 2016). "For example, CD40 stimulation may result in increased expression of VEGF and thereby promoting tumor angiogenesis, and CD40 signaling on myeloid-derived suppressor cells (MDSCs) is required for induction of T-cell tolerance and the accumulation of T regulatory cells (Tregs) in the tumor." (PMID 27385210, 2016). "Therefore, it seems that CD40 on tumor cells is closely related to the immune escape of tumors." (PMID 25992978, 2015). "Furthermore, the specific CD40+% for MDSC in tumor tissues (65.04% ± 6.71%, 50.56% ± 7.52% and 41.56% ± 6.69% from MFC-, LLC- and RM-1-injected mouse tumors, respectively) was significantly higher than the in the CD40+% in the spleen of the same mouse (p < 0.05)." (PMID 26462153, 2015). "Besides stimulation of CTL responses, agonistic anti-CD40 antibodies are known for targeting CD40+ tumor blood vessels, hereby enhancing tumor neoangiogenesis, which could give a pro-tumorigenic result." (PMID 25682197, 2015). "Thus targeting CD40 might also enhance cellular therapy through engaging the CD40L molecule on transferred tumor-specific T cells." (PMID 26101781, 2015). "Therefore, this study provides preliminary evidence that CD40 may stimulate tumor growth by enabling immune evasion via MDSC recruitment and inhibition of T cell expansion." (PMID 26462153, 2015).
tumor (continued). "Thus, by modulating the interaction between CD40 on tumor cells and CD40L on activated T cells, the efficiency of cancer immunotherapy could be increased by regulating the TGF-β production in a tumor microenvironment." (PMID 25992978, 2015). "Thus, adoptively transferred CAR engineered human T cells that are specific for pancreatic tumors, along with a CD40 agonist, might elicit tumor regression in patients." (PMID 26101781, 2015). "Thus CD40 targeted therapy may have a dual beneficial effect comprising direct tumor cell signaling, leading to growth arrest or even apoptosis, and DC-dependent stimulatory activity on antitumor T-cell immunity." (PMID 23840967, 2013). "Finally, we asked if CD40-targeted Ad5-huPSMA vaccine could induce an immune response to control tumor growth." (PMID 23056548, 2012). "Also CD40 therapy seems to skew tumor-infiltrating macrophages towards the M1 phenotype." (PMID 23217146, 2012). "Moreover, the activation of innate immune signals mediated by TLR, NLR and/or CD40 may sense DC to facilitate cross-presentation of immunogenic tumor antigens and trigger specific T cell responses." (PMID 22761839, 2012). "However, measurable immune responses and control of tumor growth were achieved only by adopting complex protocols involving adoptive transfer of antigen-specific transgenic T cells and co-administration of anti-CD40, Flt3, GMCSF and/or CpG." (PMID 21379572, 2011). "Conversely, other studies have shown that CD40 may contribute to tumor growth and metastasis." (PMID 21912605, 2011). "However, accumulating evidence has indicated that CD40 may contribute to tumor proliferation and escape through its special transduction pathway, indicating the multifaceted biological properties of CD40 in cancer." (PMID 21912605, 2011). "Thus, DCs that in the tumor microenvironment contributed to the promotion of immunosuppressive conditions, when given the appropriate stimuli, including CD40 signaling through CD40L- expression on transferred T cells, were capable of priming antitumor responses." (PMID 21076522, 2010). "Thus the presence of C4BP in close proximity to tumor cells expressing the CD40 receptor could suppress the induction of CD40-mediated apoptosis by CD154 effector cells and favour tumour cell survival." (PMID 17225862, 2007). "Thus, CD40 may represent a novel therapeutic, multifunctional target in NB because of its expression on both tumour cells and professional antigen-presenting cells." (PMID 12771917, 2003). "Since, in the present study, surface CD40 was detected on a fraction of neuroblasts from the individual tumours, CD40L-induced apoptosis of malignant cells and immune activation may cooperate in the elimination of CD40+ and CD40− neuroblasts, as already shown in a different neoplastic model." (PMID 12771917, 2003). "Paired tumor biopsies confirmed colocalization of MP0317 with fibroblast activation protein and CD40." (PMID 42067655, 2026). "Regarding the expression of additional surface proteins, especially tumor-infiltrated and to a lesser extent ascites-derived pDC expressed ICOS-L, CD86, and CD40 indicating higher pDC activity in OC tissue." (PMID 41221283, 2025). "Another strategy involves using CD40 agonists to reprogram macrophages into a less immunosuppressive state, which facilitates CD8+ T cell infiltration and transforms a ‘cold’ tumor into a ‘hot’ tumor." (PMID 40458409, 2025). "We successfully developed SNAGs targeting six independent surface markers, including the tumor antigens PDL1, CD19 and HER2 and the immunostimulatory receptor CD40." (PMID 40993428, 2025). "Clinically, therapeutic strategies targeting the tumor microenvironment (TME) such as CSF1R inhibition, CCR2/CCR5 blockade, and CD40 agonism show promise in preclinical and early-phase trials, especially when combined with immunotherapy." (PMID 40995363, 2025).
tumor (continued). "In summary, this preliminary study on leveraging the immune system response to a combination treatment of LIFE Biomaterial_anti-CD40 and FLASH-RT showed the potential recruitment of the T-lymphocytes in the tumor microenvironment." (PMID 41155910, 2025). "Engagement of the CD40 pathway significantly increases the production of pro-inflammatory cytokines like TNF-α, IL-12, and IL-6, which are crucial in driving the anti-tumor immune response and promoting inflammation." (PMID 40055311, 2025). "Our results show that miR-16 directly targets the 3′UTRs of CD40 and CD80, two important modulators of the tumor immune microenvironment." (PMID 40647495, 2025). "In germinal center (GC) B cells, the inactivation of super-enhancers disrupts signaling pathways such as CD40 and BCR, impeding normal B-cell differentiation and promoting tumor transformation." (PMID 40032852, 2025). "This vaccine consists of irradiated whole tumor cells (rWTC) with Mannan-BAM, toll-like receptor (TLR) agonists (LTA, PolyI:C, and Resiquimod) and an anti-CD40 monoclonal Antibody (mAb)." (PMID 39941108, 2025). "In preclinical models, sFLT3L alone or in combination with radiotherapy, CD40 agonists, or TLR3 agonists (e.g., poly(I:C)) improved tumor control, enhanced CD8+ T‐cell cross‐priming, and in some cases triggered abscopal effects." (PMID 40667699, 2025). "In contrast, HMDMs co-cultured with untreated A375s are associated with expression of CD40, CD80, and CD206, meaning that these macrophages have adopted a complex tumor-associated macrophage state and, if given the appropriate cues, may be manipulated into an anti-tumor state." (PMID 40539073, 2025). "Immunologic adjuvants can stimulate DC maturation, enhancing the expression of MHC-II, CD40, and CD86, thereby improving the generation of tumor-specific CD8+ T cells and promoting tumor suppression." (PMID 40813760, 2025). "ABBV-428 is a novel bispecific antibody that achieves tumor-specific immune activation by specifically binding to MSLN on the surface of tumor cells and to CD40 on antigen-presenting cells." (PMID 41400642, 2025). "As the most potent APCs in the body, DCs upregulate the expression of costimulatory molecules such as CD80, CD86, CD40, and the chemokine receptor CCR7 upon stimulation with tumor antigens." (PMID 40040692, 2025). "The immunotherapy regimen, comprising a CD40 agonist, CTLA-4, and PD-1 checkpoint blocking antibodies, was applied to assess its impact on tumor growth on the irradiated and a contralateral unirradiated tumor." (PMID 40475579, 2025). "Given the identified group of IFITM1-regulated proteins involved in immune responses, two selected proteins were further validated, CD40 and CD166, which are critical factors in tumor-immune cell interactions." (PMID 40314078, 2025). "This echoes the findings from preclinical models showing that tumor microenvironment therapeutic reprogramming via CXCR4 blockade, CD40 agonists, or TGF-β inhibition enhances Tc recruitment and restores anti-tumor activity." (PMID 41375696, 2025). "In the clinic, the tumor/stroma-targeting bispecific, fibroblast activation protein (FAP)-CD40, increased DC-LAMP+ DCs and reduced CLEC9A+ DCs (cDC1) within solid tumors, with the full results yet to be published." (PMID 41086813, 2025). "Treg cell depletion restored CD40 expression by CCR7+ DCs, enhanced immunostimulatory programs, and improved T cell-dependent tumor control." (PMID 41421339, 2025). "Emerging evidence suggests that activating neutrophils has therapeutic effects in tumor immunotherapy, including the Bacillus Calmette-Guérin (BCG), β-glucan, or a combination therapy involving anti-CD40 antibodies, TNF-α, and tumor-binding antibodies." (PMID 39925807, 2025). "MP0317, on the other hand, activates CD40+ APCs via its anti-FAP arm, which recognizes fibroblasts in the tumor microenvironment, therefore limiting toxicity to fibroblast-rich tumors." (PMID 40700292, 2025).
tumor (continued). "In vivo depletion assays confirmed that CD40‒HER2 BsAb‐11 inhibited tumour growth mainly through macrophages, B cells and T cells, as their depletion restored tumour growth." (PMID 40726342, 2025). "In preclinical settings, activating B cells with substances like CD40 stimulation and CpG-ODN demonstrated promise in improving T-cell responses and lowering tumor burden." (PMID 39996755, 2025). "In case the tumor defense relies on the activation of CD40+ host cells such as antigen-presenting cells by CD40L-expressing T cells, the tumor growth rates should be comparable in CD40 or CD40L knockout (KO) mouse strains." (PMID 40397730, 2025). "Gemcitabine induces tumor antigen release (such as HMGB1) and reduces myeloid-derived suppressor cells (MDSCs), while CD40 agonists enhance the expression of co-stimulatory molecules (CD80/86), drive CD8+ T cell infiltration and inhibit Treg function." (PMID 41293424, 2025). "The elevated levels of CD40, CD86, and MHC-I confirmed the increased dendritic cell maturation and activation in PAK1KO tumours." (PMID 40943273, 2025). "Functional assays and scRNA‐seq of TAMs in 3D culture spheroids further demonstrated that intra‐cellular heme‐NRF2 signalling activated cancer‐promoting features in TAMs, inducing tumour cell EMT and resistance to IFNγ and anti‐CD40 antibodies." (PMID 40677104, 2025). "Significantly, SAg-exposure enhanced inflammatory activation of CLL tumour cells, which acquired CD38, CD40, CD86, while downregulating CD27 (p≤0.005), even in cultures from ibrutinib-treated CLL patients." (PMID 40207214, 2025). "We have demonstrated that targeting CD40, in addition to Delta-24-RGD, generates durable anti-tumor immunity." (PMID 40578365, 2025). "CD40, a pivotal B cell surface molecule in mediating T cell responses, has been shown to enhance TIL-B density and inhibit tumor growth when targeted with antibodies in mesothelioma models." (PMID 41285707, 2025). "Based on their mechanisms of action, CD40, TLRs and STING agonists have been developed to target macrophages, with the aim of reinstating immune surveillance and reducing tumor growth." (PMID 40453088, 2025). "CD40, a TNF receptor family member expressed on tumor cells and antigen-presenting cells, including macrophages, induces proinflammatory cytokine release and upregulation of CD80 and CD86 upon activation, sustaining T cell responses." (PMID 40936918, 2025). "When examining the tumor microenvironment, PLX3397 abrogated the Delta-24-RGD+anti-CD40-dependent recruitment of DCs." (PMID 40578365, 2025). "Combining RAS(ON) and CDK4/6 inhibition with a CD40 agonist results in durable regressions and CD4 T cell–dependent tumor-immune equilibrium." (PMID 40299790, 2025). "Additional CD40 agonists and ICI combinations were recently summarized elsewhere, with ICIs able to enhance the function of tumor-specific CD40-primed T cells in the TME." (PMID 41086813, 2025). "In TAM reprogramming strategies, shifting M2-like to M1-like phenotypes reprograms TAMs toward pro-inflammatory M1-like states via CD40 agonists, TLR activators, or radiotherapy, which showed anti-tumor effects in preclinical models." (PMID 40422244, 2025). "Tumor immune checkpoints (TICs) such as PDCD1 (PD-1), CTLA4, IDO1, and CD40 are critical regulators of immune responses and have emerged as promising therapeutic targets in cancer immunotherapy." (PMID 40918116, 2025). "These molecules likely contribute to anti‐tumour immunity through distinct mechanisms—CD40 by enhancing dendritic cell activation and cytotoxic T cell responses, and CCL4 by potentially recruiting anti‐tumour immune cells to the tumour microenvironment." (PMID 40682474, 2025). "An agonistic CD40 antibody, APX005M, has been developed to enhance immune activity against the tumour and induce tumour cell apoptosis." (PMID 38774284, 2024).
tumor (continued). "Quantification analysis of signal intensity from the tumors demonstrated that Nano/CLDN18.2 and NanoBE exhibited significantly higher accumulation compared to Nano/TM and Nano/CD40, highlighting the pivotal role of anti-CLDN18.2 scFv in tumor targeting." (PMID 38468289, 2024). "In contrast, TAM reprogramming with agonistic anti-CD40 monoclonal antibodies increases the intratumoral accumulation and longevity of TCR-engineered T cells and promotes tumor cell apoptosis." (PMID 38185636, 2024). "Even more, we identified a cDC2 population expressing the Fc gamma receptor I (FcγRI)/CD64 in tumors and LN that displayed high levels of CD40 and CCR7 indicating involvement in T cell-mediated tumor immunity." (PMID 38631706, 2024). "The CD155/TIGIT axis is essential to support immune evasion; when combined with PD-1 blockade plus CD40 activation, the CD155/TIGIT targeting stimulates a robust anti-tumor response in preclinical models of PDAC." (PMID 38817612, 2024). "Specifically, we genetically engineered two single chain variable fragments (scFv) onto cell membrane: anti-CD40 scFv for engaging with macrophages and anti-Claudin18.2 (CLDN18.2) scFv for interacting with tumor cells." (PMID 38468289, 2024). "These engineered B cells acquire CD40 activity, effectively stimulating neoepitope-specific CD8+ tumor-infiltrating lymphocytes (TILs) ex vivo." (PMID 39720721, 2024). "In vitro experiments have demonstrated that specific blockade of tumor-secreted IL-10 and TGF-β can lead to the up-regulation of CD40, thereby enhancing the cytolytic activity of effector T cells against CCA cells." (PMID 39845973, 2024). "To delve deeper into the effect of TLR5 agonist treatment on macrophage function, particularly the activation of T cell immune responses, we examined the co-stimulatory molecules CD40 and CD80 on macrophages from the tumor and spleen." (PMID 38630304, 2024). "In comparison to control tumors, those overexpressing miR-29 exhibited the following changes: (i) Elevated levels of anti-tumor cytokines such as CCL5 and CCL11, the transmembrane protein CD40, and the angiogenesis inhibitor endostatin." (PMID 38890285, 2024). "Compared to naïve DCs, DCs challenged with tumor supernatant exhibited significantly suppressed expression of MHC II, CD40, CD80, and CD86." (PMID 38164187, 2024). "Transforming growth factor-β (TGF-β) secreted by CAFs limits T cell infiltration into the tumor while also downregulating the expression of MHC-II, CD80, and CD40 on the surface of dendritic cells in the TME, suppressing anti-tumor immunity." (PMID 38605943, 2024). "The combination of a CD40 agonist and the FMS-like tyrosine kinase 3 ligand has also been found to enhance tumor immunity and responsiveness to radiotherapy by mobilizing conventional DCs." (PMID 38167055, 2024). "Intriguingly, anti-tumor activity was lost when anti-CD40 was eliminated together with either anti-CTLA-4 or CpG, while some anti-tumor activity was retained when the anti-CTLA-4 and CpG were both eliminated." (PMID 38731089, 2024). "CD40/CD40L interaction also participates in regulating thrombosis, tissue inflammation, hematopoiesis and tumor cell fate." (PMID 39845973, 2024). "Our vaccination consists of mannan‐BAM‐anchored irradiated whole tumor cells, Toll‐like receptor (TLR) agonists [lipoteichoic acid (LTA), polyinosinic‐polycytidylic acid (poly (I:C)), and resiquimod (R‐848)], and anti‐CD40 monoclonal antibody." (PMID 38298111, 2024). "Consistent with the in vitro results, the proportion of mature DCs (CD11C+CD40+, CD80+, or CD86+) in tumor tissues and tumor-draining lymph nodes (TDLNs) was highly upregulated compared to that in the control group." (PMID 38994018, 2024). "Herein, we have developed a novel CD40 agonist formatted into the ADAC design and assessed the lead drug compounds impact on T cell expansion, toxicity, and tumor growth in various model systems." (PMID 39500897, 2024).